RNU6-558P (RNA, U6 small nuclear 558, pseudogene)
Gene: Small nuclear RNA gene on chromosome 12 (116,782,105 to 116,782,208, forward strand). Ensembl gene ENSG00000201382.
Homologues: Orthologues: chimpanzee U6 (99% identical), macaque U6 (94% identical), pig U6 (82% identical). Paralogues in human: RNU6-1060P (92% identical), RNU6-132P (92% identical), RNU6-15P (92% identical), RNU6-266P (92% identical), RNU6-949P (92% identical), RNU6-1011P (91% identical), RNU6-12P (91% identical), RNU6-13P (91% identical), RNU6-166P (91% identical), RNU6-26P (91% identical), RNU6-31P (91% identical), RNU6-32P (91% identical), and 1285 more.